INS (insulin)
Diseases named in the same sentence as INS in open-access papers (continued):
Sharing a sentence is not in itself a finding about the gene and the disease.
Insulin resistance (continued). "There are other recognized methods to determine insulin resistance, such as QUICKI, HOMA-IR, and Matsuda index; however, it is necessary to know the fasting insulin level, which we did not have in our study and is also very difficult to obtain in primary care doctors’ offices." (PMID 37432258, 2023). "The insulin-sensitizing medicines thiazolidinediones and metformin usually stimulate AMPK in various tissues, even though a direct connection between AMPK initiation and the reduction of insulin resistance in humans has not been established." (PMID 37241737, 2023). "In addition, data on other glucose-related parameters, such as the Homeostatic Model Assessment of Insulin Resistance (HOMA-IR), and insulin levels were not available." (PMID 37848993, 2023). "However, there is no well-defined cutoff point that differentiates normal from abnormal insulin sensitivity in youth and there is no universally accepted, clinically useful, numeric expression in the HOMA-index that defines insulin resistance." (PMID 37234798, 2023). "We hypothesized that if dysregulation of skeletal muscle β‐catenin is involved in the development of diet‐induced insulin resistance, short‐term HFD feeding would have a lesser impact on insulin responsiveness in mice lacking skeletal muscle β‐catenin." (PMID 36807886, 2023). "Fasting plasma glucose, insulin and HOMA insulin resistance index did not change in both groups." (PMID 35391843, 2022). "Thus, in T1DM, there is an insufficient or absent secretion of insulin, which is treated solely by insulin substitution, while in T2DM, there is insulin resistance which is treated by different types of drugs." (PMID 35629188, 2022). "Similarly, in the subgroup analysis based on the insulin resistance status, as the TyG index increased, the prevalence of pre-HTN and HTN increased in both the non-insulin and the insulin resistant groups (all P < 0.001)." (PMID 36309720, 2022). "The homeostasis model assessment-estimated insulin resistance (HOMA-IR) index, a means for detecting β-cell function and IR, is widely used at present, but it has limited value in subjects receiving insulin treatment or those who do not have functioning beta cells." (PMID 35524263, 2022). "Therefore, CNS insulin levels and insulin resistance in AD are likely not driven by alterations in IDE activity and insulin degradation." (PMID 35884888, 2022). "The latest data show that n-6 PUFAs, but not n-3 PUFAs, may improve homeostasis model assessment—insulin resistance (HOMA-IR), lowering insulin in healthy subjects." (PMID 36296979, 2022). "Likewise, NMN administration did not affect the homeostatic model assessment of insulin resistance (HOMA-IR), an indicator of hepatic insulin sensitivity in blood analysis." (PMID 35927255, 2022). "Given that we show DCAF7 regulates insulin signaling in vitro, and dFoxo localization in Drosophila tissue, a limitation of this study is that a role for DCAF7 in glucose metabolism and the development of insulin resistance was not examined." (PMID 36248734, 2022). "The Homeostasis Model Assessment for Insulin Resistance (HOMA-IR) significantly (P< 0.05) decreased after 12 weeks treatment with metformin; there were non-significant decreases in plasma glucose and insulin concentrations." (PMID 35038311, 2022). "The improved classifier for insulin resistance, consisting of ten microbial genera, presented an advanced classification (AUROC = 0.93), whereas the improved classifier for insulin-sensitive individuals failed to distinguish participants with fatty liver diseases from the healthy." (PMID 36528695, 2022). "Although the level of insulin was not significantly increased by the YSHS, both HbA1c and C-peptide were ameliorated by the drug, suggesting YSHS possessed beneficial effects against insulin resistance in DN." (PMID 35935814, 2022).
Insulin resistance (continued). "Insulin resistance was common amongst PLWD, and negative attitudes towards insulin may have been fuelled by family or community misconceptions about insulin." (PMID 35924623, 2022). "In a subgroup analysis of people with T2D, there was very low certainty evidence that zinc supplementation reduced FBG (WMD −20.34 mg/dL, CI −29.04 to −11.64) but not HbA1c or measures of insulin resistance (HOMA-IR, fasting insulin) when compared with placebo." (PMID 35684094, 2022). "Systemic insulin resistance appears to play no role in RAPA‐generated hyperglycemia in NcZ10 mice as RAPA‐ and RAPA/MET‐treatments actually reduced systemic insulin resistance to a level comparable with that of lean, insulin sensitive C57BL6J." (PMID 35986566, 2022). "However, insulin resistance upregulated expression of PHLPP1 by 4.2 fold (lane 1 vs. lane 3) and of PHLPP2 by 2.3 fold (lane 1 vs. lane 3) irrespective of insulin stimulation." (PMID 36376971, 2022). "Several studies have shown both a positive correlation with the Quantitative Insulin Sensitivity Check Index (QUICKI), used as an insulin sensitivity indicator, and a negative correlation with the Homeostasis Model Assessment (HOMA) index, used for the degree of insulin resistance." (PMID 34070202, 2021). "However, no benefits were observed on insulin resistance and sensitivity, measured by HOMA-IR, quantitative insulin sensitivity index (QUICKI) and HbA1c and by the gold standard 2-step, hyperinsulinemic euglyceminc clamp." (PMID 34439410, 2021). "The consequences of insulin resistance in obesity and DM2 may be secondary to three main mechanisms: chronic inflammation, lack of insulin effect, or hyperinsulinemia." (PMID 33648564, 2021). "First, because the NHIS-HEALS cohort did not collect serum insulin levels, we could not validate the correlation between the TG/HDL-C ratio and insulin resistance." (PMID 34503545, 2021). "Interestingly for parameters of insulin sensitivity (HOMA-IR and Matsuda index), the most advanced insulin resistance appeared not in T2D but in prediabetic patients." (PMID 34938272, 2021). "Some studies have reported limitations of HOMA-IR in subjects with high fasting glucose levels and indicated that the fasting insulin value, rather than HOMA-IR, could be a surrogate measure of insulin resistance." (PMID 33407104, 2021). "Although the decrease in AKT activity may not be solely responsible for the ample and diverse insulin-resistant outcomes, AKT phosphorylation remains a useful index of insulin resistance." (PMID 34336862, 2021). "However, the improved glucose tolerance was not accompanied by similar outcomes in fasting glucose, insulin, and HOMA-IR index, although small but significant improvements were observed in TyG index for insulin resistance in both trained groups." (PMID 34371972, 2021). "A meta-analysis of 30 studies that evaluated the effect of resveratrol on glucose, insulin, and glycated hemoglobin levels and insulin resistance (HOMA-index) reported a significant reduction of fasting glucose and insulin levels but no significant changes in glycated hemoglobin and HOMA-index." (PMID 33923263, 2021). "PTP1B overexpression is strictly related to insulin resistance, whereas PTP1B inhibition or genetic ablation improve glucose homeostasis, cellular sensitivity to both insulin and leptin, and resistance to diet-induced obesity, without inducing hypoglycaemia or toxic effects." (PMID 34677434, 2021). "Type 2 diabetes mellitus (T2DM) is the predominant type of metabolic disease, accounting for 90–95% of cases, which are characterized by high blood glucose, insulin resistance (Homeostatic Model Assessment for Insulin Resistance [HOMA-IR]), and relative lack of insulin." (PMID 34371867, 2021). "Meanwhile, both intensity exercise could not effectively alleviate the insulin resistance induced by TCDD, but high intensity exercise could promote compensatory insulin secretion to maintain glucose homeostasis." (PMID 34948750, 2021).
Insulin resistance (continued). "Five of the eight articles investigated the association between breakfast skipping and glycemic profile (fasting glucose, Homeostatic Insulin Resistance Assessment Model (HOMA-IR), acute insulin response, and insulin sensitivity), but none of them found a significant association." (PMID 34932697, 2021). "The homeostasis model assessment of insulin resistance index (HOMA) is the most used index of IR (Insulin Resistance), validated in overweight and obese patients but not in normal-weight PCOS subjects, who can still present with increased insulin secretion by an oral glucose tolerance test (OGTT)." (PMID 34357331, 2021). "Moreover, it was suggested that the serum insulin level is a predictor of the serum level of GAL and that the high serum level of GAL observed could be associated with the increase in body weight reported in obese (non-diabetic) individuals and to insulin resistance." (PMID 33802616, 2021). "The use of an indirect yet well validated method evaluating insulin resistance such as the HOMA-IR is clearly preferable to glycaemic levels alone, even though insulin clamps were not performed due to their complexity and the obvious difficulty to encompass large populations." (PMID 34393806, 2021). "For example, because younger adolescents, aged 10–13 years, undergo a period of transient insulin resistance indicated by an increasing HOMA-IR, the absence of change in fasting insulin and HOMA-IR over our intervention, could indicate a positive adaptation." (PMID 34095194, 2021). "Interestingly, plasma BDNF concentrations were negatively correlated with insulin resistance using the homeostatic model assessment version 2 (HOMA2-IR), but not with insulin concentrations." (PMID 34992516, 2021). "There was no increased use of oral anti‐diabetic drugs or insulin dosage with any treatment, although this could be expected in view of the BCAA‐mediated increase in insulin resistance described in animal models." (PMID 34519439, 2021). "Given that insulin signaling inhibits GSK3β, the lack of the proper intracellular activity mediated by PI3K/AKT suggests that GSK3β would play a deleterious role in neurons after the onset of insulin resistance." (PMID 34356637, 2021). "However, an early study showed that monocyte binding to insulin in SCI patients was normal, and not impaired by peripheral insulin resistance." (PMID 33100956, 2020). "The homeostatic model assessment of insulin resistance (HOMA-IR) is often used in research and correlated with direct measures of insulin mediated glucose uptake, but its application is hampered by lack of standardization of insulin assays." (PMID 31992297, 2020). "On the basis that a positive effect of IGFBP-1 on endothelial repair is only observed in insulin-resistant and not insulin-sensitive mice, we next investigated whether IGFBP-1 modulates angiogenesis in the setting of insulin resistance." (PMID 32190801, 2020). "Some intervention studies on diabetic patients report a correlation between high intake of green tea catechins and improved insulin levels or improved blood glucose levels, while others do not confirm the effects of EGCG on amelioration of insulin resistance or glucose tolerance." (PMID 32635492, 2020). "In keeping with synaptic dysfunction in non-obese insulin resistance, activity between synapses was shown to trigger the mobilization of GLUT4 (the insulin-sensitive glucose carrier) from intracellular sources into axonal plasma membranes, a process that is mediated by the metabolic sensor AMPK." (PMID 33536868, 2020). "Majority of studies were conducted in subjects having metabolic or endocrinologic abnormalities such as T2DM, insulin resistance, obesity, metabolic syndrome (MetS) or PCOS, but some studies investigated antidepressant effects of insulin in subjects without metabolic abnormalities." (PMID 32971941, 2020).
Insulin resistance (continued). "Also, different assessment of insulin sensitivity/resistance was employed; all trials used at least insulinemia and HOMA-IR as parameters of insulin resistance and none of the clinical trials used the gold standard technique." (PMID 33292434, 2020). "Secondly, insulin resistance is one of the most significant mechanisms for NAFLD among the nonobese individuals, but the initial study design did not allow for the measurement of the insulin levels." (PMID 32454814, 2020). "Importantly, in line with previous studies, our protocol successfully induced insulin resistance in both adipose cell types as demonstrated by the 50% decrease in insulin-mediated phosphorylation of Akt and IRS-1, without changes in insulin potency." (PMID 32718202, 2020). "The present study further showed that cholesterol might even be protective against palmitate-induced hypothalamic insulin resistance ex vivo, as CHO + PA was not as detrimental as PA treatment to insulin action on hypothalamic brain slices." (PMID 32456175, 2020). "On the one hand, elevated CTRP1 levels lowers blood glucose levels without altering insulin or adiponectin levels, and on the other hand, high CTRP1 concentrations protect from diet-induced obesity and insulin-resistance, while CTRP1 knockout mice developed insulin resistance and hepatic steatosis." (PMID 31083558, 2019). "On a LFD without developing insulin resistance, our LTCFDN mice showed increased gluconeogenesis as well as lipogenesis, suggesting that β-cat/TCF may serve as a “paradoxical effector” of hepatic insulin signaling." (PMID 31589598, 2019). "A high intake of fat without weight-gain induces insulin resistance in rodents, whereas a recent human study showed that a 6 week LCHF diet with 64 percentage of energy (E%) fat, did not decrease insulin sensitivity in slightly overweight males." (PMID 31920704, 2019). "Also, insulin resistance markers (OGTT values, HOMA-IR, and fasting insulin) can also help in predicting non-responsiveness to clomiphene." (PMID 31423417, 2019). "However, we were unable to investigate markers of insulin resistance (e.g., Homeostatic model assessment HOMA) due to lack of insulin data; such a measure provides useful data due to the insulin resistance exhibited during adolescence." (PMID 31035361, 2019). "Also, CPR was decreased at 12 months, suggesting improvement of insulin resistance, although CPR alone is not sufficient to evaluate either insulin sensitivity or insulin secretion." (PMID 31167663, 2019). "However, contrary to most reports in non-pregnant populations that have noted positive relationships between AP and insulin resistance or T2DM, there does not seem to be a relationship between AP intake and insulin sensitivity in this cohort of pregnant women." (PMID 31514469, 2019). "In our study, the suppression of hypothalamic PTEN in HFD-fed rats reversed insulin resistance without exerting effects on food intake, indicating that the HFD-induced blockage of hypothalamic insulin signals, such as IRS-1 serine phosphorylation, exist upstream from PI 3-kinase." (PMID 30875909, 2019). "In the same study, negative correlations were reported between CTRP5 and insulin, FBG, and insulin resistance, and lower circulating CTRP5 level was determined to be a statistically noteworthy risky factor for T2DM and NAFLD after adjustment for potential confounders." (PMID 29964236, 2019). "In the Insulin Resistance Intervention after Stroke (IRIS) trial, performed in non-diabetic but insulin-resistant patients with a history of stroke or transient ischemic attack, pioglitazone was able to lower the risk for recurrent stroke or myocardial infarction compared with placebo therapy." (PMID 31540142, 2019). "In our study, insulin levels in the non-STZ groups were slightly lower than those in the STZ groups, and blood glucose levels of STZ mice were elevated significantly, which led to insulin resistance and induce type II diabetes." (PMID 31781274, 2019).
Insulin resistance (continued). "Regarding insulin resistance, our results show decreased glycemia in ABG-treated rats 30 minutes after an oral bolus of glucose compared to non-treated rats, pointing out to a slight insulin-sensitizing effect." (PMID 30642033, 2019). "From these results, one could speculate that liver fat reduction may not necessarily precede the improvements in hepatic insulin resistance, given that fasting insulin, and to some extent also FGF-21, may partly reflect changes in hepatic insulin sensitivity." (PMID 31685793, 2019). "Although a link between the phosphorylation of neural IRS1 at mSer307, mSer612, and mSer632/635 and brain insulin resistance has been proposed, brain insulin resistance is not yet defined, and the phosphorylation of IRS1 at Ser sites emerges in insulin-dependent and insulin-independent manners." (PMID 31426549, 2019). "Third, we did not have measurements of insulin and BCAA levels beyond baseline assessment, which limited us to evaluate the evolution of insulin resistance and regression dilution of BCAAs could not be excluded." (PMID 30917546, 2019). "Since the serum levels of insulin, leptin and adiponectin were not routinely measured in AHF patients, we could not clarify the relationship between glycemic gap and insulin resistance." (PMID 31000758, 2019). "Fasting insulin levels and the homeostatic model assessment for insulin resistance (HOMA-IR) values were normal in SUC mice, indicating that these animals did not develop insulin resistance." (PMID 30257452, 2018). "Our multiple linear-regression model analyzing fasting glucose levels against 10- and 12-Z,E-HODE/LA, insulin and leptin/adiponectin or against insulin and leptin/adiponectin predicted IGT and insulin resistance without the OGTT, with specificity and sensitivity >98%." (PMID 29610560, 2018). "However, it should be emphasized that, althoughfasting insulin dosage and HOMA-IR are relevant in epidemiological studies to checkfor insulin resistance, there is no justification for this screening in clinicalpractice when assessing overweight children." (PMID 30365811, 2018). "However, p38αFab-KO mice maintained the insulin-induced translocation after the HFD, perhaps due to the fact that these animals did not gain weight and were protected against diet-induced insulin resistance." (PMID 29979672, 2018). "Systemic insulin resistance was significantly induced in patients with heart failure in the LVAD study, whereas in our model, pressure overload-mediated LV failure was not accompanied by an impairment of insulin sensitivity or glucose tolerance." (PMID 29320510, 2018). "In addition, important measurements, such as immuno-reactive insulin (IRI), to estimate Homeostasis model assessment-Insulin Resistance (HOMA-IR) were not collected." (PMID 28203292, 2017). "Moreover, with the lack of NLRP3 and IL-1β, our findings revealed the improved insulin signaling cascade in vitro, suggesting the NLRP3 inflammasome as an important determiner of insulin resistance." (PMID 29096724, 2017). "However, reductions in serum insulin and HOMA insulin resistance measured after non-restricted days were significantly lower than CER only with the lower energy IER (p = 0.02), but not the less restrictive IER regimen (p = 0.21)." (PMID 28106818, 2017). "Exercise reduces insulin resistance, but it is not known whether TRPC1 is involved in exercise-induced insulin sensitivity." (PMID 29074621, 2017). "However, insulin levels are well correlated with HOMA-IR (r = 0.85; p<0.001); thus, in the current population, HOMA-IR offers no advantages in evaluating insulin resistance." (PMID 28323845, 2017). "Generally, BCAAs have been shown to induce insulin resistance by phosphorylation of serine IRS-1 via activating mammalian targets of the rapamycin complex 1 (mTORC1) signaling pathway, and lead to a negative feedback loop of insulin signaling." (PMID 28574481, 2017).